INS (insulin)
Diseases named in the same sentence as INS in open-access papers (continued):
Sharing a sentence is not in itself a finding about the gene and the disease.
Hyperglycemia (continued). "An insulin-resistant phenotype is characterized by elevated fasting glucose levels, hyperglycemia, impaired glucose metabolism and normal insulin levels, no longer resulting in an adequate response by targeted tissue." (PMID 33806509, 2021). "The term prediabetes refers to a state of impaired insulin signaling and hyperglycemia that has not yet reached the threshold for diagnosis of diabetes." (PMID 34138882, 2021). "Hyperglycemia was seen at the highest dose levels and patients without a diagnosis of diabetes occasionally required the institution of insulin or an oral hypoglycemic agent." (PMID 34611148, 2021). "Diabetic neuropathy is thought to occur as a result of hyperglycemia and lack of neurotrophic support from insulin/C-peptide." (PMID 33532012, 2021). "Once insufficient insulin secretion fails to compensate the high demand for insulin, the hyperglycemia occurs." (PMID 33686020, 2021). "Since the SSTR2a elicited a minor increase in glucagon concentrations during hyperglycemia in the perfused pancreas, it could be speculated that α cell–derived GLP-1 would be released in parallel, which could stimulate insulin release." (PMID 33434183, 2021). "These animals had fasting and fed hyperglycaemia as a consequence of reduced insulin and enhanced proinsulin secretion without changes in insulin sensitivity." (PMID 33419045, 2021). "While hypoglycemia is a common feature of overdose with sulphonylureas, insulin, ethanol, non-selective beta-blockers and paracetamol, hyperglycemia is not a common feature of poisonings." (PMID 33672765, 2021). "KS patients with hyperglycemia tended to have decreased insulin sensitivity and hyperinsulinemia and increased insulin secretion compared with hyperglycemia patients without KS." (PMID 34852815, 2021). "If insulin secretion fails to compensate adequately for defects in insulin action, regardless of the exact cellular mechanism, then hyperglycemia develops and further promotes oxidative stress and inflammatory responses that can result in vascular damage." (PMID 34069950, 2021). "Insulin is no longer available to enable the cellular removal of glucose from the bloodstream, leading to rising glucose levels and resulting in hyperglycaemia (high blood sugar)." (PMID 34121470, 2021). "Additionally, omega‐3 fatty acids were reported to decrease FBG, fasting plasma insulin, and HOMA‐IR index, possibly by suppression of hyperglycemia‐mediated oxidative stress usually observed in PCOS." (PMID 32994975, 2020). "Persistence of hyperglycemia, despite the action of ABA and in excess of muscle energy requirement, then results in insulin release and in the activation of the metabolic responses to nutrient abundance (glycogen and fatty acid synthesis, adipocyte differentiation and accumulation of triglycerides)." (PMID 32526875, 2020). "The metabolic disorder is recognized as noninsulin dependent form of diabetes landmarked by hyperglycaemia primarily because of body's inability to either produce insulin or respond to it." (PMID 32884568, 2020). "Stress hyperglycemia was partially iatrogenic in about 65% of cases and was quickly resolved by treatment of the primary illness without need for insulin administration." (PMID 33261643, 2020). "Although systematic insulin and glucose concentration were not different, severe hyperglycemia and hypoinsulinemia were found in steers with acute acidosis before euthanization." (PMID 32373641, 2020). "Altogether, these studies cast doubt on the beneficial actions of SGLTi in the absence of hyperglycaemia and suggest that anti-atherogenic effects are exerted by decreasing glucose levels independently of insulin action." (PMID 33287201, 2020). "Reduced insulin gene dosage did not consistently result into fasting hyperglycaemia in these studies although it offered protection against some of the effects of hyperinsulinemia." (PMID 33365205, 2020).
Hyperglycemia (continued). "Subjects with absence of insulin in the body face very high levels of blood glucose (BG) (hyperglycemia), which can lead to long-term micro- and macrovascular complications." (PMID 32399164, 2020). "Il1r1−/− mice were protected from transitory hyperglycemia and did not present disturbances in insulin levels in the serum." (PMID 32150895, 2020). "In contradiction to previous tesa in vivo studies, no major improvements in hyperglycemia (serum HbA1C) and serum insulin levels were detected in the treated mice compared to the untreated animals." (PMID 31918918, 2020). "Given the clinical significance of postprandial hyperglycaemia as a predictor of adverse outcomes, the finding that HOMA insulin sensitivity improves in young, lean, and healthy adult females while postprandial glucose deteriorates is novel and worthy of further investigation." (PMID 32707917, 2020). "Acute hyperglycemia, independent of insulin levels, significantly attenuates forearm endothelium-dependent, but not independent, vasodilation in healthy humans." (PMID 33322540, 2020). "The lack of response of tissues to insulin results in a state of transient and unpredictable hyperglycaemia and hyperinsulinemia, together with an inflammatory signature that predisposes an individual to metabolic syndrome and type 2 diabetes (t2D)." (PMID 33066504, 2020). "Hyperglycemia in T2DM is initially accompanied by compensatory hyperinsulinemia, but as the disease progresses, oxidative stress triggers apoptosis of the beta cells, and the amount of insulin produced by the pancreas gradually declines." (PMID 33396883, 2020). "MNCV was not different between groups (P = 0.8; control: 34.7 ± 5.1; STZ-DIO vehicle: 33.4 ± 5.5; STZ-DIO low-insulin: 32.8 ± 5.1; STZ-DIO high-insulin: 33.6 ± 7.4 m/s), suggesting no large nerve fiber damage after 16 weeks of hyperglycemia." (PMID 32832565, 2020). "None of the patients had persistent, 2 h severe stress hyperglycemia levels (over 200 mg/dl) to consider a more active, insulin targeted therapeutic approach." (PMID 32120784, 2020). "The majority of patients in the Dula group were also treated with insulin, suggesting that Dula cannot suppress GC-induced hyperglycemia without insulin." (PMID 32381085, 2020). "As such, the results of the current study apply directly to adults with T2D, specifically those who are not on more than two oral hypoglycaemic agents or insulin or with uncontrolled hyperglycaemia (HbA1c > 9.5%)." (PMID 33105701, 2020). "Hyperglycemia in patients with advanced renal failure allows study of the theoretical predictions in a closed system because it can be treated with insulin infusion and with no or minimal changes in the external balance of sodium, potassium and water." (PMID 32984372, 2020). "The ER of β-cells in particular functions at the upper limits of its capacity to synthesize insulin, and the UPR induced by postprandial hyperglycemia allows β-cells to transiently surpass these limits to increase insulin production and meet the demands of the body during the absorptive state." (PMID 33457426, 2020). "Many anesthesiologists are reluctant to administer insulin to non-diabetics with hyperglycemia intraoperatively due to potentially devastating effects of hypoglycemia under anesthesia." (PMID 32381036, 2020). "Chromium may enhance insulin sensitivity by increasing skeletal muscle cellular insulin signaling and improve the response of these alterations in the glucose metabolism, which contributes to overcoming HFD-induced hyperglycemia." (PMID 32260278, 2020). "Hyperglycemia should be managed by initiation of metformin and staged treatment intensification with a dipeptidyl peptidase 4 inhibitor, with a switch to a GLP-1 receptor agonist and initiation of insulin, as required, to achieve and maintain glycemic control." (PMID 33434154, 2020).
Hyperglycemia (continued). "GCK-MODY is generally non-progressive and characterized by preserved insulin secretion, mild fasting hyperglycemia present from birth, and minor postprandial glucose excursions." (PMID 33292863, 2020). "The data on insulin administration suggests that there are patients with hyperglycemia in the perioperative period that this study does not capture." (PMID 32381036, 2020). "Then, our murine T2D model recapitulates weight gain, hyperglycemia, elevated levels of A1C, and insulin resistance but not the dysregulation of lipids observed in human patients with this disease." (PMID 32194998, 2020). "Insulin is an essential hormone that metabolizes glucose, and a lack of insulin leads to hyperglycemia." (PMID 32190485, 2020). "In order to determine whether expression of INS-FUR alone would reverse hyperglycaemia in the diabetic NOD mice and establish normal glucose tolerance, the animals received an i.p. injection of the AAV8-INS-FUR-mCherry vector." (PMID 33023100, 2020). "Stress hyperglycemia, even in non-diabetic patients, is a marker of stress response in critically ill patients and results from a release of contra-insulin hormones (i.e., glucocorticoids and catecholamines)." (PMID 33053694, 2020). "When not promptly treated with insulin, these patients develop marked hyperglycemia and ketosis with consequent hyperketonemia, proteolysis and lipolysis." (PMID 32774865, 2020). "The increase in fasting hyperglycemia observed in the BlvraFatKO mice did not correlate with any changes in fasting insulin levels between the groups." (PMID 32131495, 2020). "However, exposure of human islets to prolonged hyperglycaemia suppresses PTBP1 expression and insulin biosynthesis, possibly due to the concomitant upregulation of microRNA (miR)-133a, which binds to the 3′-UTR of PTBP1 mRNA." (PMID 32894308, 2020). "Within intact islets, hyperglycemia instead inhibits α-cell exocytosis, but not in T2D or when paracrine inhibition by insulin or somatostatin is blocked." (PMID 32312960, 2020). "Neonatal hyperglycemia is often treated with insulin infusion, but it is still uncertain which concentration of blood glucose could be associated with increased risk of tissue damage, leading to a lack of consensus with regard to the cutoff level to treat hyperglycemia." (PMID 33306685, 2020). "Patients experienced hyperglycemia, recovered with hyperglycemic medication (insulin, metformin, glimepiride), and did not require study drug dose modification." (PMID 32578154, 2020). "After a 5 h exposure to LPS, mice receiving IV dextrose did not demonstrate increases in proinflammatory cytokines compared to saline-infused mice, and while decreases in insulin sensitivity were observed, the mice did not develop overt hyperglycemia." (PMID 32977395, 2020). "Given that hyperglycemia was rescued by RPSE supplementation, we assessed whether this benefit of RPSE is dependent on gaining insulin sensitivity." (PMID 32842462, 2020). "In addition, in PC3 cells, high glucose treatment enhanced insulin-driven EMT, suggesting an additional role of hyperglycemia in the activation of EMT in patients with T2D." (PMID 33207809, 2020). "A significant hyperglycemia was found in the maltodextrin-treated group during the prelunch period, without any significant changes in insulin and glucagon between the two groups." (PMID 32971830, 2020). "Previous results showed that hyperglycemia disrupts vascular homeostasis mainly through inhibitory effects on several factors including vascular endothelial growth factor (VEGF), platelet-derived growth factor (PDGF), activated protein C (APC), and insulin." (PMID 32695298, 2020). "Without the response to insulin, glucose is not efficiently cleared from the circulating plasma and hyperglycemia arises." (PMID 32977673, 2020). "The authors revealed that BDNF decreased hyperglycemia, independent of changes in food intake, and lowered blood glucose levels in an insulin-independent manner." (PMID 32012942, 2020).
Hyperglycemia (continued). "Patients in type 1 are characterized by hyperglycemia and hyperinsulinemia, usually lacking insulin conflict." (PMID 32880218, 2020). "Upon nutrient uptake, insulin promotes glucose storage in the form of glycogen in the liver to avoid postprandial hyperglycemia; while in the fasted state, the liver supplies ∼90% of endogenous glucose via hepatic glucose production (HGP) when the insulin level is low." (PMID 32917816, 2020). "In this scenario, the combined short-term physical exercise protocol was able to reverse hyperglycemia and improve insulin secretion and its sensitivity, even without reducing body mass." (PMID 32847099, 2020). "Type 1 diabetes (T1D) is characterised by the autoimmune destruction of pancreatic beta (β) cells, resulting in a lack of insulin secretion and hyperglycaemia." (PMID 33023100, 2020). "STZ successfully provoked hyperglycemia, and BBR treatment significantly decreased fasting blood glucose and improved glucose intolerance in STZ-induced diabetic mice, suggesting that berberine decreased hyperglycemia in an insulin-independent manner." (PMID 31976031, 2020). "In addition, AF burden of diabetic animals was reduced when both hyperglycemia and impaired atrial GLUT trafficking was rescued by in vivo insulin treatment." (PMID 32903422, 2020). "Compared to the diabetogenic phenotype of F1 females, adult-exposed dams did not display fasting hyperglycemia nor an abnormal glycemia response to insulin and showed a more subtle glucose intolerance on IPGTT." (PMID 33093533, 2020). "Type I Diabetes (T1D) is an autoimmune disease-derived disorder wherein there is a lack of a sufficient level of insulin to regulate blood glucose, which leads to hyperglycemia and subsequent organ damage." (PMID 31935938, 2020). "Taken together, our data demonstrate that loss of Raptor had detrimental impacts on proinsulin production, metabolic coupling of insulin secretion in β-cells, but the abnormal increase in proinsulin/insulin ratio and defects in CPE expression were the consequences of hyperglycemia." (PMID 32439909, 2020). "In T1DM, the pancreas terminates or reduces insulin production due to pancreatic β-cell destruction, whereas in T2DM, the cells manifest low sensitivity towards insulin and consequently both types lead to hyperglycemia." (PMID 33066443, 2020). "These animal models are characterized by reduced islet β cell numbers, non-fasting or fasting hyperglycemia, decreased insulin secretion, and low glucose tolerance during glucose stimulation." (PMID 33011961, 2020). "Insulin secretion in response to glucose is reduced and this mechanism results in non-progressive fasting hyperglycaemia in patients." (PMID 33162936, 2020). "This is a normal response to blood glucose dynamics as consumption of more carbohydrates and less insulin intake can derive blood glucose dynamics into the hyperglycemia region (high blood glucose levels) if there is no physical activity session." (PMID 32784179, 2020). "In metabolically healthy individuals, the negative effect of postprandial hyperglycemia on endothelial function is counterbalanced by a parallel increase in insulin-induced nitric oxide (NO) production by endothelial cells." (PMID 32664350, 2020). "This short‐term metformin treatment enhanced insulin sensitivity of the db/db mice, visualized by reduced glucose area under the curve in insulin tolerance test, but hyperglycemia was not reduced." (PMID 31342643, 2020). "The effect of hyperglycaemia with and without additional insulin was explored at a low and high intensity of exercise (40% vs 70% VO2peak) on glucose utilization (GUR), carbohydrate oxidation, non-oxidative glucose disposal (NOGD), and muscle glycogen." (PMID 31707476, 2020).
Hyperglycemia (continued). "A locus for hyperglycemia in GTT was mapped to segment B-D in KK-Ay mice (Nidd6k), a locus for serum insulin was mapped to segment B-E in NZO (Nidd3), and loci for hyperglycemia in GTT were mapped to segment E in SMXA-5 (T2dm5sa), TSOD (Nidd4), and Akita mouse (Dbm2)." (PMID 32703163, 2020). "After learning the personalized strategies, the well-trained DRL agent delivers an optimal insulin bolus that effectively reduced the postprandial hyperglycemia without increasing hypoglycemia." (PMID 32899979, 2020). "Insulin levels were reduced in STZ-treated mice, and hyperglycemia was detected." (PMID 31992349, 2020). "One is that fasting hyperglycaemia in T2D is a result of processes independent of insulin signalling such as autonomic signalling or other insulin independent mechanisms." (PMID 33365205, 2020). "The major factors contributing to T1D-related hyperglycemia are reduced or no insulin secretion, decreased glucose utilization by the peripheral tissue, and increased glucose production." (PMID 31935938, 2020). "T1DM is caused by autoimmune destructionof pancreatic beta-cells, leading to the total absence of insulin secretion and,consequently, hyperglycemia." (PMID 31479096, 2020). "The increased prevalence of any ROP and of severe ROP seen clinically and experimentally is possibly explained by decreased IGF1 expression mediated through decreased insulin signaling and not necessarily by hyperglycemia itself." (PMID 33004691, 2020). "With the exception of MLD-STZ at 1 week post-administration (for which no animals developed hyperglycemia), a similar increase in insulin staining intensities was observed for hyperglycemic mice at all time points analyzed." (PMID 32999405, 2020). "In order to determine whether the FFO procedure had a stimulatory effect on pancreatic transdifferentiation of the livers and correction of hyperglycemia, diabetic mice received the AAV8/piggyBac-INS-FUR-mCherry vector and FFO surgery 7 days later." (PMID 33023100, 2020). "Along with these findings, supplementation with DCI reduces InsR in numerous experimental models affected by hyperglycemia or T2D, which also indicates that the DCI may be more effective than MI in restoring insulin sensitivity and glycogen synthesis." (PMID 32252239, 2020). "Lentinus edodes did not reduce the mother hyperglycemia, however it promoted an improvement in maternal glucose tolerance and an increase in insulin levels." (PMID 31717560, 2019). "Although hyperglycemia is normally corrected by insulin secretion, the plasma insulin concentrations of the OLETF rats were not affected by the treatment." (PMID 31614552, 2019). "Basal plasma insulin concentrations were 4-fold higher in the obese than the lean subjects (P = 0.008) and increased 5-fold in both groups during hyperglycemia, independent of changes in plasma acetate concentrations." (PMID 31404159, 2019). "In contrast to these finding, exposure of INS-1β cells to HT (0.1–30 μM) did not relieve the hyperglycemia-induced decline in insulin secretion." (PMID 31234300, 2019). "According to these guidelines, the mainstay of hyperglycemia management in the hospital is the administration of insulin, given its high efficacy, flexibility, and lack of interference with most other pharmacotherapies or organ dysfunctions." (PMID 31261760, 2019). "Fasting plasma glucose concentrations were not different among groups, and glucose and insulin concentrations increased (P < 0.05) during the hyperglycaemia clamp." (PMID 31665811, 2019). "Although hyperglycemia has been shown to induce sICAM-1, while insulin inhibits it, neither permissive underfeeding nor IIT showed any significant changes in serum sICAM-1 in our study." (PMID 31052277, 2019). "Our present data suggested that cancer patients are not exempted from developing hyperglycemia due to low insulin sensitivity, which induces cognitive impairment." (PMID 31661025, 2019).